HHAT (hedgehog acyltransferase)
Description:
Palmitoyl acyltransferase that catalyzes N-terminal palmitoylation of hedgehog (DHH, IHH or SHH) morphogens, promoting their maturation. Promotes the transfer of palmitoyl-CoA from the cytoplasmic to the luminal side of the endoplasmic reticulum membrane, where hedgehog palmitoylation occurs. Required for hedgehog signaling during limb development (By similarity). Plays a role in proper testis cord formation and the differentiation of Leydig cells.
Synonyms: MART-2; MART2; SKI1; FLJ10724; Skn; ski; rasp; sit; GUP2; NNMS
Tractability: Small molecule: a structure with a bound ligand is known; a high-quality ligand is known. Antibody: UniProt predicts a signal peptide or a membrane-spanning region. PROTAC: ubiquitination databases record sites on it; a small molecule that binds it is known.
Target class: Enzyme; Transferase
Chemical probes: RU-SKI 43, RUSKI-201
Gene: Protein-coding gene on chromosome 1 (210,328,252 to 210,676,298, forward strand). Ensembl gene ENSG00000054392.
Subcellular location: Endoplasmic reticulum membrane; Golgi apparatus membrane
Subcellular location (Human Protein Atlas): Golgi apparatus
Pathways (Reactome):
Disease: HHAT G278V doesn't palmitoylate Hh-Np
Signal Transduction: Hedgehog ligand biogenesis
Gene Ontology:
Molecular function: protein binding; protein-cysteine S-palmitoyltransferase activity; acyltransferase activity, transferring groups other than amino-acyl groups; palmitoyltransferase activity
Biological process: positive regulation of smoothened signaling pathway; protein maturation
Cellular component: endoplasmic reticulum; endoplasmic reticulum membrane; Golgi apparatus; Golgi membrane
Genetic constraint (gnomAD): Loss-of-function variants: 42 observed, 69.17 expected, observed/expected ratio (o/e) 0.61, 90% interval 0.47 to 0.79. The upper end of that interval is the gene's LOEUF score, 0.79, which puts it in group 3 of 6, group 1 being the genes least tolerant of losing a copy. Missense variants: 588 observed, 608.07 expected, observed/expected ratio (o/e) 0.97, 90% interval 0.9 to 1.03. Synonymous variants: 222 observed, 252.65 expected, observed/expected ratio (o/e) 0.88, 90% interval 0.79 to 0.98.
Homologues: Orthologues: chimpanzee HHAT (95% identical), macaque HHAT (92% identical), rabbit HHAT (88% identical), guinea pig HHAT (86% identical), rat Hhat (85% identical), mouse Hhat (84% identical), dog HHAT (83% identical), pig HHAT (79% identical), tropical clawed frog hhat (61% identical), zebrafish hhat (48% identical), Drosophila melanogaster rasp (25% identical), Caenorhabditis elegans hhat-1 (25% identical), and 1 more. Paralogues in human: HHATL (27% identical).
Diseases named in the same sentence as HHAT in open-access papers:
HHAT is named in the same sentence as 26 diseases in open-access papers, as found by Europe PMC text mining. Sharing a sentence is not in itself a finding about the gene and the disease. The quoted sentences say what the papers report.
holoprosencephaly (5 papers, 2012 to 2022). Holoprosencephaly (HPE) is a complex brain malformation resulting from incomplete cleavage of the prosencephalon, occurring between the 18th and 28th day of gestation, and affecting both the forebrain and face, which results in neurological manifestations and facial anomalies of variable severity. "HHAT mutations can also be indicative of severe acrania‐holoprosencephaly‐agnathia craniofacial defects." (PMID 32864857, 2020). "Here we demonstrate for the first time that Hedgehog acyltransferase (Hhat) loss-of-function leads to holoprosencephaly together with acrania and agnathia, which highlights the importance of Hh signaling in complex craniofacial disorders." (PMID 23055936, 2012).
lung squamous cell carcinoma (5 papers, 2016 to 2024). "Indeed, total RNA sequencing of mRNA obtained from oncosphere cells after siRNA-mediated knockdown of the PRKKC gene, in combination with Meta pathway analysis, showed that the HHAT gene was strongly associated with stem maintenance in lung squamous cell carcinoma." (PMID 30338036, 2018). "Specifically, the literature reports that HHAT overexpression is often found in many tumors (e.g., in lung squamous cells carcinoma)." (PMID 36395113, 2022). "PKCι can also phosphorylate the transcriptional regulator of stemness, SOX2, enhancing its binding to the promoter of Hedgehog acyltransferase (HHAT) to facilitate the Hh target genes expression in lung squamous cell carcinoma." (PMID 30214681, 2018). "PKCι phosphorylates Thr118 of SOX2, which upregulates hedgehog acyltransferase (HHAT) and maintains the stem-like and tumorigenic properties of lung squamous cell carcinoma (LSCC)." (PMID 38331879, 2024).
ovarian carcinoma (3 papers, 2022 to 2025). A malignant neoplasm originating from the surface ovarian epithelium. "This study focused on an HLA-A*02:06 restricted TCR (302-TIL) specific for a L75F mutation in hedgehog acyltransferase (HHAT) identified from a patient with ovarian cancer." (PMID 35222422, 2022). "The HHATp8F neoepitope was first identified in ovarian cancer patients and derives from the hedgehog acyltransferase (HHAT) oncogene." (PMID 38045695, 2023). "SHH, HHAT, PTCH1, and PTCH2 overexpression further improved the survival rates of ovarian cancer patients, particularly when optimal debulking was possible." (PMID 40565349, 2025). "We analyzed the mRNA expression profiles of HH-related genes—SHH, HHAT, PTCH1, GLI1, GLI2, GLI3, and SUFU—in two ovarian cancer cell lines." (PMID 40565349, 2025). "To assess their potential prognostic value, we analyzed the correlation between the expression levels of the following eight components of the Hedgehog signaling pathway on the progression-free (PFS) and overall survival (OS) in ovarian cancer: SHH, GLI1, GLI2, GLI3, PTCH1, PTCH2, HHAT, and SUFU." (PMID 40565349, 2025).
breast carcinoma (2 papers, 2015 to 2021). "Therefore, the potential of HHAT inhibition has been tested in various cancers, including breast cancer and pancreatic ductal adenocarcinoma." (PMID 33906647, 2021).
chondrodysplasia-pseudohermaphroditism syndrome (2 papers, 2020 to 2022). "Nivelon-Nivelon-Mabille syndrome, also known as chondrodysplasia-pseudohermaphroditism syndrome (OMIM: 600092) is caused by a mutation in HHAT." (PMID 36230363, 2022). "HHAT is a hedgehog acyltransferase, and diseases associated with HHAT include chondrodysplasia‐pseudohermaphroditism syndrome and ancylostomiasis." (PMID 32864857, 2020). "Of these, four genes were determined to be related to bone development (PLXNA2 with prognathism, HHAT with the complex Nivelon-Nivelon-Mabille Syndrome, MBOAT2 with chondrocyte differentiation, and ITGAV with chondrodystrophy), and one to calcium homeostasis (HPCAL1)." (PMID 36230363, 2022).
cleft lip (1 paper, 2025). Congenital defect in the upper lip where the maxillary prominence fails to merge with the merged medial nasal prominences. "For instance, the genetic correlations of disorders such as cleft lip, craniofacial abnormalities, and microcephaly, specifically related to genes like ZFHX3 and HHAT, are consistent with previous research findings." (PMID 39928610, 2025).
Gorlin syndrome (1 paper, 2017). "Thus, the downregulation of HHAT in patient-derived iPSCs might also contribute to tumorigenesis in patients with Gorlin syndrome." (PMID 29088246, 2017).
Hydrocephalus (1 paper, 2023). Hydrocephalus is an active distension of the ventricular system of the brain resulting from inadequate passage of CSF from its point of production within the cerebral ventricles to its point of absorption into the systemic circulation. "A newborn 46,XY girl (DSD 12) presented hydrocephalus, skeletal malformations, bilateral anophtalmos and agenesis of the corpus callosum carried a very rare homozygous variant (p.R312S) in HHAT gene (DSD 12)." (PMID 36631813, 2023).
non-small cell lung carcinoma (1 paper, 2024). A group of at least three distinct histological types of lung cancer, including non-small cell squamous cell carcinoma, adenocarcinoma, and large cell carcinoma. "HHAT knockdown suppresses Shh pathway activation and the development of non-small cell lung cancer cells in vitro, as well as tumor growth in vivo in mice xenografts." (PMID 39980969, 2024).
osteosarcoma (1 paper, 2024). A usually aggressive malignant bone-forming mesenchymal neoplasm, predominantly affecting adolescents and young adults. "Although the roles of SP110, HHAT, MORC4, PAGE5, MAP7, and CAMK1G in osteosarcoma have rarely been reported, their involvement in other types of cancer has been revealed." (PMID 39980969, 2024).
pancreatic cancer (1 paper, 2018). "Because it has been previously reported that HHAT inhibition by RU-SKI 43 negatively affected Akt and mTOR pathways in pancreatic cancer cells, we also assessed the impact of RU-SKI 43 on Akt and mTOR pathways in SAS and eSAS cells." (PMID 30338036, 2018).
schizophrenia (1 paper, 2024). A major psychotic disorder characterized by abnormalities in the perception or expression of reality. "In addition to the biological role of the HHAT gene, the region of its chromosomal localisation has been suggested as a candidate region for schizophrenia by several genetic linkage studies and cytogenetic findings." (PMID 38920990, 2024). "It has been proposed that the regulation of HHAT–Shh could be involved in the complex multifactorial pathophysiology of schizophrenia, also based on dysregulations in the neurodevelopment and neurotransmission of dopaminergic circuits." (PMID 38920990, 2024).
cancer (9 papers, 2014 to 2024). A tumor composed of atypical neoplastic, often pleomorphic cells that invade other tissues. "Accordingly, HHAT knockout leads to a loss-of-function HH phenotype, and HHAT has been identified as a potential cancer drug target." (PMID 34890564, 2021). "Recent studies by our group and others provided proof of principle that inhibiting HHAT function is a valid method of inhibiting Hh signaling in cancer (14, –, 16)." (PMID 25505265, 2015). "By contrast, hedgehog acyltransferase (HHAT) gene expression is associated with cell growth and is suggested to play a role in cancer by promoting the N-terminal palmitoylation of sonic hedgehog (SHH), which is required for proper SHH signaling involved in the control of cell growth." (PMID 30338036, 2018). "Small molecule inhibitors of HHAT have been investigated as potential anti-cancer agents." (PMID 29088246, 2017). "Hedgehog acyltransferase (HHAT) is the enzyme in the endoplasmic reticulum that palmitoylates Hedgehog proteins, is a member of a small subfamily of membrane-bound O-acyltransferase proteins that acylate secreted proteins, and is an important drug target in cancer." (PMID 25505265, 2015).
tumor (6 papers, 2012 to 2025). "The two-group comparison (metastasis/tumor) revealed an almost two-fold upregulation of the HHAT gene." (PMID 40565349, 2025). "We observed other markedly under-expressed genes (P<0.05) included tumour-suppressor candidates that negatively regulate the Hh pathway (SUFU, GAS1, RAB23) and genes encoding inhibitory proteins (HHIP, HHAT)." (PMID 22361633, 2012). "A study on BC cell lines demonstrated that inhibition of hedgehog acyltransferase HHAT, one of the main enzymes in SHH synthesis, led to a decrease in the growth of HER2+ tumor cells." (PMID 36294994, 2022). "In lung squamous cell carcinoma (LSCC) tumor-spheres, SOX2 activation induced upregulation of Hh acyltransferase (HHAT), a critical component that palmitoylates Hh ligands, and induced autocrine pathway activation to drive growth of LSCC tumor-spheres but not bulk LSCC cells nor LAD tumor-spheres." (PMID 32108165, 2020).
HHAT also shares sentences with these, for which no sentence is quoted: Obesity (2 papers); ancylostomiasis (1); Diseases of the respiratory system (1); fibroma (1); idiopathic pulmonary fibrosis (1); Kleefstra syndrome (1); lung carcinoma (1); microcephaly (1); pancreatic ductal adenocarcinoma (1); schizoaffective disorder (1); sex cord-stromal tumor (1); type 2 diabetes (1).